HIBCH (3-hydroxyisobutyryl-CoA hydrolase)
Description:
Hydrolyzes 3-hydroxyisobutyryl-CoA (HIBYL-CoA), a saline catabolite. Has high activity toward isobutyryl-CoA. Could be an isobutyryl-CoA dehydrogenase that functions in valine catabolism. Also hydrolyzes 3-hydroxypropanoyl-CoA.
Synonyms: HIBYLCOAH
Tractability: Small molecule: a structure with a bound ligand is known. PROTAC: ubiquitination databases record sites on it; its protein half-life has been measured.
Target class: Enzyme; Hydrolase
Gene: Protein-coding gene on chromosome 2 (190,189,735 to 190,344,193, reverse strand). Ensembl gene ENSG00000198130.
Subcellular location: Mitochondrion
Subcellular location (Human Protein Atlas): Mitochondria
Pathways (Reactome):
Disease: 3-hydroxyisobutyryl-CoA hydrolase deficiency
Metabolism: Branched-chain amino acid catabolism
Gene Ontology:
Molecular function: 3-hydroxyisobutyryl-CoA hydrolase activity
Biological process: L-valine catabolic process; branched-chain amino acid catabolic process
Cellular component: mitochondrial matrix; mitochondrion
Genetic constraint (gnomAD): Loss-of-function variants: 16 observed, 22.44 expected, observed/expected ratio (o/e) 0.71, 90% interval 0.48 to 1.08. The upper end of that interval is the gene's LOEUF score, 1.08, which puts it in group 4 of 6, group 1 being the genes least tolerant of losing a copy. Missense variants: 200 observed, 211.85 expected, observed/expected ratio (o/e) 0.94, 90% interval 0.84 to 1.06. Synonymous variants: 76 observed, 73.01 expected, observed/expected ratio (o/e) 1.04, 90% interval 0.86 to 1.26.
Gene-disease validity (ClinGen):
ClinGen rates the evidence that HIBCH causes each of these diseases.
3-hydroxyisobutyryl-CoA hydrolase deficiency (autosomal recessive): Definitive.
Leigh syndrome (autosomal recessive): Definitive. A progressive neurological disease defined by specific neuropathological features associating brainstem and basal ganglia lesions.
Homologues: Orthologues: chimpanzee HIBCH (99% identical), macaque HIBCH (95% identical), dog HIBCH (88% identical), mouse Hibch (82% identical), rat Hibch (82% identical), pig HIBCH (78% identical), guinea pig HIBCH (78% identical), rabbit HIBCH (69% identical), tropical clawed frog hibch (68% identical), zebrafish hibch (65% identical), Drosophila melanogaster Hibch (49% identical), Caenorhabditis elegans hach-1 (47% identical). Paralogues in human: ECHS1 (23% identical), ECHDC2 (21% identical), AUH (20% identical), CDY1B (17% identical), CDY2A (17% identical), CDY2B (17% identical), CDYL (17% identical), CDY1 (16% identical), CDYL2 (16% identical), ECHDC1 (15% identical), ECHDC3 (15% identical), ECH1 (15% identical), and 1 more.
Diseases named in the same sentence as HIBCH in open-access papers:
HIBCH is named in the same sentence as 45 diseases in open-access papers, as found by Europe PMC text mining. Sharing a sentence is not in itself a finding about the gene and the disease. The quoted sentences say what the papers report.
colorectal cancer (7 papers, 2019 to 2024). A primary or metastatic malignant neoplasm that affects the colon or rectum. "Elevated HIBCH expression negatively correlates with the survival of colorectal cancer patients and is associated with tumor proliferation, anti-apoptosis, and reduced autophagy." (PMID 39280009, 2024). "In models of colorectal cancer, disruption of valine catabolism via the inhibition of HIBCH reduces TCA metabolite levels, inhibits tumour xenograft growth and reduces the occurrence of drug-acquired resistance to bevacizumab." (PMID 39025852, 2024). "As a crucial enzyme of valine catabolism, HIBCH was reported to promote oxidative phosphorylation and tumor growth in colorectal cancer." (PMID 37469520, 2023). "Colorectal cancers express higher levels of HIBCH, and its function depends on its localization in mitochondria, and blocking the function of HIBCH not only can inhibit the growth of cancer cells but also can improve the efficacy of targeted therapy." (PMID 37638005, 2023). "For example, valine can be reprogramed by targeting HIBCH to treat colorectal cancer, leucine deprivation has been shown to inhibit proliferation and induces apoptosis in breast cancer cells, and isoleucine has been shown to prevent liver metastases." (PMID 33945541, 2021). "This study is to explore the critical roles of 3-hydroxyisobutyryl-CoA hydrolase (HIBCH) in colorectal cancers (CRC) and to develop a new therapy returning valine metabolism homeostasis." (PMID 31409769, 2019). "To investigate the function of HIBCH in CRC, we overexpressed and silenced HIBCH in HCT116 cells (a colorectal carcinoma cell line)." (PMID 31409769, 2019). "delved into the implications of HIBCH in the progression and treatment of colorectal cancer." (PMID 37638005, 2023).
Leigh syndrome (4 papers, 2018 to 2024). "3-hydroxy isobutyl-CoA hydrolase (HIBCH) deficiency is a recently described, rare inborn error of valine metabolism associated with a Leigh syndrome-like phenotype, neurodegenerative symptoms, and caused by recessive mutations in the HIBCH gene." (PMID 38975013, 2024). "Inherited mutations in the ECHS1 and HIBCH enzymes of the valine catabolic pathway lead to the development of Leigh syndrome, a neurological disorder characterized by mitochondrial defects." (PMID 34961760, 2021). "Biallelic variants in HIBCH manifest as neurodevelopmental delay, dystonia, and ataxia with MRI findings consistent with Leigh syndrome." (PMID 33426505, 2020). "Recently, two siblings were described with fatal Leigh disease who had increased excretion of several metabolites that are features of 3-hydroxyisobutyryl-CoA hydrolase (HIBCH) deficiency." (PMID 30029642, 2018).
Ataxia (3 papers, 2020 to 2025). Ataxia refers to impaired coordination of voluntary muscle movement. "An uncommon condition of the mitochondrial valine metabolism known as 3‐Hydroxyisobutyryl‐CoA hydrolase (HIBCH) deficiency can cause organic aciduria, motor delay, hypotonia, ataxia, dystonia, seizures, poor eating and developmental regression or delay." (PMID 40286336, 2025). "The second case of HIBCH deficiency was also a male infant but it was the first reported case of a baby born to nonconsanguineous parents and presenting with ataxia, dysmetria, tremors, developmental delay, and metabolic acidosis." (PMID 38975013, 2024).
developmental delay (3 papers, 2021 to 2024). "The significant clinical presentations were developmental delay/regression, hypotonia, encephalopathy, feeding difficulties and dystonia, and the last 4 symptoms were more specific in patients with Leigh/Leigh-like syndrome caused by HIBCH mutation in our cohort." (PMID 33762937, 2021).
Dystonia (3 papers, 2020 to 2025). An abnormally increased muscular tone that causes fixed abnormal postures. "The symptoms of hypotonia, dystonia, encephalopathy, and feeding difficulties were more common in patients with HIBCH mutations." (PMID 33762937, 2021). "The phenotype of Leigh/Leigh-like syndrome caused by HIBCH mutations was not significantly different from other gene mutations, except for more comment presentations with hypotonia, dystonia, and acute encephalopathy." (PMID 33762937, 2021).
HIBCH deficiency (2 papers, 2021 to 2024). "Pathogenic variations in the HIBCH gene are associated with an autosomal recessive HIBCH deficiency (MIM: #250620)." (PMID 38975013, 2024). "HIBCH mutations were first identified to cause HIBCH deficiency (HIBCHD, OMIM #250620) in 2007, and it was reported that it could lead to Leigh/Leigh-like disease due to secondary oxidative phosphorylation (OXPHOS) defects." (PMID 33762937, 2021). "To date, just 31 HIBCH gene mutations have been reported, with 34 patients on a broad phenotypic spectrum ranging from early death to just movement disorder with survival into adulthood, although the estimated incidence of HIBCH deficiency was 1 in ∼130,000 individuals." (PMID 33762937, 2021).
Obesity (2 papers, 2020 to 2023). Accumulation of substantial excess body fat. "ACAA2 and ACAD8 are proteins mainly catalyze dehydrogenation steps of β-oxidation processes in mitochondrial fatty acids catabolism, HIBCH involving in energy metabolism by regulating fat hydrolysis in obesity mice." (PMID 32053710, 2020). "Moreover, liver HIBCH mRNA expression was significantly elevated in those with NASH and obesity compared to those without." (PMID 37084480, 2023).
ovarian carcinoma (2 papers, 2021 to 2022). A malignant neoplasm originating from the surface ovarian epithelium. "A seven-hub-molecule-signature model (RRAS2, HIST1H2BK, ALB, RPL23A, HIBCH, RPS20, and EIF3E) from those 1198 mtDEPs is established to predict the survival time of ovarian cancer." (PMID 35498135, 2022). "A seven-hub-molecule-signature model (HIBCH, HIST1H2BK, ALB, EIF3E, RPS20, RRAS2, and RPL23A) from a multivariate regression analysis can predict the survival risks of ovarian cancer." (PMID 35498135, 2022).
Alzheimer disease (1 paper, 2025). A progressive, neurodegenerative disease characterized by loss of function and death of nerve cells in several areas of the brain leading to loss of cognitive function such as memory and language. "Using bioinformation approaches, we discovered HIBCH and MGME1 as novel biomarkers to identify the underlying processes of mitochondrial dynamics that cause impaired mitochondrial function in Alzheimer's disease, and HIBCH was linked to Tau metabolism." (PMID 40286336, 2025).
colorectal adenocarcinoma (1 paper, 2019). The most common type of colorectal carcinoma. "GSEA of colorectal adenocarcinoma data set from TCGA showed that oxidative phosphorylation signature was enriched in the samples with high expression of HIBCH." (PMID 31409769, 2019).
deficiencies (1 paper, 2023). "In the case of ECHS1 and HIBCH genes, encoding a hydratase and a hydrolase enzyme, respectively, in the final valine metabolism, LSS is the most common clinical manifestation of these genetic deficiencies." (PMID 37628588, 2023).
Epstein-Barr virus infection (1 paper, 2022). An infection that is caused by Epstein-Barr virus. "Finally, four significant KEGG enrichment pathways were identified (P < 0.05): beta-Alanine metabolism (SMOX, HIBCH), Pathways in cancer (GLI2, AR, TXNRD3, TRAF3, FGF16), Non-homologous end-joining (MRE11), Epstein-Barr virus infection (TRAF3, PSMD13, SIN3A)." (PMID 36330154, 2022). "Finally, the results of KEGG enrichment analysis showed four significantly enriched pathways (P < 0.05): beta-Alanine metabolism (SMOX, HIBCH), Pathways in cancer (GLI2, AR, TXNRD3, TRAF3, FGF16), Non-homologous end-joining (MRE11), Epstein-Barr virus infection (TRAF3, PSMD13, SIN3A)." (PMID 36330154, 2022).
fatty liver (1 paper, 2023). "We hypothesized that perturbation of HIBCH expression in human hepatocytes could modulate mechanisms of hepatic lipid accumulation and metabolic flexibility, and may thereby be a causal player in the development of fatty liver." (PMID 37084480, 2023). "We uncovered a positive correlation between hepatic HIBCH mRNA expression and hepatic fat in humans, an inhibitory effect of HIBCH on oxidative phosphorylation and a stimulatory effect on ROS generation as mechanisms linking HIBCH to fatty liver and metabolic disease." (PMID 37084480, 2023).
fatty liver disease (1 paper, 2023). A reversible condition wherein large vacuoles of triglyceride fat accumulate in liver cells via the process of steatosis. "We found elevated HIBCH mRNA in the liver of patients with fatty liver disease and visceral adiposity, and increased HIBCH mRNA and extracellular 3-HIB concentrations concomitant with substantial lipid accumulation in cultured human hepatocytes exposed to FAs." (PMID 37084480, 2023).
Insulin resistance (1 paper, 2023). Increased resistance towards insulin, that is, diminished effectiveness of insulin in reducing blood glucose levels. "Recent studies have shown that plasma 3-HIB, an intermediary catabolite of the BCAA valine, which is formed via the enzyme HIBCH, is strongly elevated in insulin resistance, and that 3-HIB modulates lipid uptake and storage in muscle and adipose tissue." (PMID 37084480, 2023). "The valine (branched-chain amino acid) metabolite 3-hydroxyisobutyrate (3-HIB), produced by 3-Hydroxyisobutyryl-CoA Hydrolase (HIBCH), is associated with insulin resistance and type 2 diabetes, but implicated tissues and cellular mechanisms are poorly understood." (PMID 37084480, 2023). "We also found increased AKT phosphorylation upon HIBCH knockdown, suggesting that HIBCH may contribute to hepatic insulin resistance, in line with a reduced insulin response upon 3-HIB exposure of myocytes and adipocytes." (PMID 37084480, 2023).
kidney cancer (1 paper, 2023). Primary or metastatic malignant neoplasm involving the kidney. "In our study, HIBCH was suggested to be reduced in expression in ccRCC and associated with a good prognosis, and the results of in vitro experiments also showed that HIBCH inhibits the migration ability of kidney cancer cells." (PMID 37638005, 2023). "Subsequently, we further explored the effect of abnormal expression of HIBCH on the migration ability of kidney cancer cells to elucidate its role in the metastasis of kidney cancer." (PMID 37638005, 2023). "Moreover, by extracting RNA from kidney cancer and paraneoplastic tissues for qPCR, the same results were obtained, and the cancer tissues expressed lower levels of HIBCH." (PMID 37638005, 2023).
lactic acidosis (1 paper, 2023). Metabolic acidosis characterized by the accumulation of lactate in the body. "A recent Spanish study demonstrated that HIBCH deficiency was completely correlated to LSS, and ECHS1 deficiency displayed LSS, but also fatal neonatal lactic acidosis and paroxysmal dystonia." (PMID 37628588, 2023).
liver fibrosis (1 paper, 2023). "Exploring HIBCH as a therapeutic target is further motivated by the markedly increased extracellular MMA concentrations we observed upon HIBCH overexpression, as MMA (an established marker of vitamin B12 status) has been identified as a marker of advanced liver fibrosis in patients with NAFLD." (PMID 37084480, 2023).
metastatic tumours (1 paper, 2024). "Conversely, we found that PCa cells with neuroendocrine properties (MR42D) were insensitive to HIBCH knockdown, consistent with our investigations in patient metastatic tumours." (PMID 39025852, 2024).
osteosarcoma (1 paper, 2015). A usually aggressive malignant bone-forming mesenchymal neoplasm, predominantly affecting adolescents and young adults. "Across all Ewing and osteosarcoma cell lines eleven genes were found to be either significantly (P < 0.05, Bonferroni correction) repressed (KIF20A, IDH1, SCD, GPSM2, EIF2AK4, HIBCH) or induced (STK19, DNAJC24, MTG2, FAM175B, CYB5D1) following non DNA-damaging XI-006 treatment (0.5 μM)." (PMID 26095524, 2015).
tumor (7 papers, 2019 to 2024). "High levels of HIBCH expression are associated with lower tumor grades and stages, reflecting its relationship to clinical variables." (PMID 37638005, 2023). "Inversely, tumours that possessed neuroendocrine PCa features (NEPC) were negatively associated with these genes, notably HIBCH and SUCLG2." (PMID 39025852, 2024). "The upregulation of HIBCH in HT-29 tumor xenograft treated with bevacizumab was observed by global proteomic profiling." (PMID 31409769, 2019). "HIBCH was also induced in the tumour compartment, with expression frequently localized to margins and haemorrhagic areas." (PMID 31121957, 2019). "We found that HIBCH expression significantly increased in the tumor tissues as compared with the para-carcinoma tissues." (PMID 31409769, 2019). "Expression of HIBCH was observed in both brain and tumour compartments, with variable staining intensity in each." (PMID 31121957, 2019). "We venture to speculate in this paper that there may be some as-yet-unknown mechanism of interaction between MRPL3 and HIBCH capable of modulating the progression of tumor and thus interfering with respiration and the TCA cycle." (PMID 39868366, 2024). "Based on these findings, there may be a mechanism through which HIBCH interacts with ccRCC’s immune microenvironment, which may influence tumor development and treatment response." (PMID 37638005, 2023). "Furthermore, SBF-1 treatment reduced HIBCH expression in mitochondria in tumor tissues compared with vehicle-treated xenografts." (PMID 31409769, 2019). "Taken together, the in vivo study strongly suggested that blocking mitochondrial localization of HIBCH by SBF-1 could be effective in inhibiting tumor growth in CRC xenograft models." (PMID 31409769, 2019). "Therefore, a possible consequence of HIBCH induction in reactive glia could be that valine degradation intermediates and/or products are transferred to the tumour compartment." (PMID 31121957, 2019). "Despite our identification of ARhigh tumours experiencing enhanced MitoS scores, patients with metastatic double-negative tumours also possessed a similar level of HIBCH expression, possibly explaining the heightened sensitivity of ARnull PC3 cells to HIBCH inhibition." (PMID 39025852, 2024).
cancer (4 papers, 2019 to 2023). A tumor composed of atypical neoplastic, often pleomorphic cells that invade other tissues. "Loss of BCKDK led to reduced expression of BCAT1 and HIBCH, candidate genes augmented in several cancers." (PMID 34526485, 2021). "Mutations in the HIBCH gene are present at low levels (0.5–6.0%) in many kinds of cancers." (PMID 31409769, 2019). "The pharmacological blockade of HIBCH mitochondrial localization with SBF-1 resulted in decreased cancer cell growth and increased autophagy, collectively contributing to the antitumor effect both in vitro and in vivo." (PMID 31409769, 2019). "Thus, the critical roles of HIBCH in cancer cell growth and valine homeostasis suggest the potential for new therapies targeting valine metabolism by antagonizing HIBCH." (PMID 31409769, 2019). "HIBCH’s role in cancer is currently unknown in the current state of research." (PMID 37638005, 2023). "Then, HIBCH protein level was evaluated by immunohistochemical staining in 17 paired CRC tissues and the para-carcinoma tissues." (PMID 31409769, 2019).
metabolic disease (2 papers, 2023 to 2024). A congenital disorder (due to inherited enzyme abnormality) or acquired (due to failure of a metabolically important organ) disorder resulting from an abnormal metabolic process. "In hepatocytes, HIBCH expression positively correlates with liver fat content, inhibits oxidative phosphorylation, and enhances reactive oxygen species (ROS) production, mechanisms that potentially linked to metabolic diseases." (PMID 39280009, 2024).
cardiovascular diseases (1 paper, 2024). "Our primary focus is on their roles in cardiovascular diseases, the result uncovered involvement of ADK, BLVRA, ALDH1B1, UGDH, and HIBCH." (PMID 39369254, 2024).
HIBCH also shares sentences with these, for which no sentence is quoted: Acute encephalopathy (1 paper); breast carcinoma (1); colon cancer (1); Encephalopathy (1); Failure to thrive (1); gestational diabetes (1); maple syrup urine disease (1); metabolic acidosis (1); metabolic myopathies (1); Methylmalonic aciduria (1); movement disorder (1); Neurodevelopmental delay (1); neurological disorder (1); non-small cell lung carcinoma (1); ovarian tumours (1); paroxysmal dystonia (1); prostate adenocarcinoma (1); prostate carcinoma (1); ptosis (1); Tetralogy of Fallot (1); type 2 diabetes (1).